PLK1 (polo like kinase 1)
Diseases named in the same sentence as PLK1 in open-access papers (continued):
Sharing a sentence is not in itself a finding about the gene and the disease.
cancer (901 papers, 2002 to 2026). A tumor composed of atypical neoplastic, often pleomorphic cells that invade other tissues. "The oncogenic significance of PLK1 is further underscored by its association with chemotherapy resistance, and its inhibition has been shown to enhance the sensitivity of cancer cells to both chemotherapy and radiotherapy." (PMID 41539998, 2026). "PLK1 plays a crucial role in cell cycle regulation and cancer development, and its dysregulation has been implicated in the prognosis of a variety of malignancies." (PMID 40612941, 2025). "Overall, this study concentrated on predicting deleterious and potential nonsynonymous single nucleotide polymorphisms (nsSNPs) in the PLK1 gene that alter protein functions and contribute to various types of cancer using in silico approaches." (PMID 41404416, 2025). "Targeting PLK1 has emerged as a promising therapeutic strategy for cancer treatment, as the overexpression of PLK1 has been associated with tumor development and progression." (PMID 40064886, 2025). "PLK1 inhibitors can cause cancer cell death by interfering with multiple phases of mitosis, which has been widely investigated in various cancer trials." (PMID 40665355, 2025). "PLK1 has been associated with the occurrence and growth of malignant tumours in many studies, and PLK1 can promote tumour cell growth." (PMID 40462502, 2025). "Previous studies have reported that the dysregulation of PLK1 is highly associated with a wide range of cancers, including breast, esophagus, stomach, lung, ovary, prostate, pancreas, head, and neck." (PMID 41404416, 2025). "For example, PLK1 (Polo-like kinase 1) gene overexpression has been associated with cell proliferation of tumor cells in cancer and cardiomyocytes and reducing apoptosis in MI." (PMID 40270498, 2025). "There is an association between high PLK1 and low immune cell infiltration and antitumor activity in many cancer types." (PMID 40615690, 2025). "This association with tumorigenesis suggests PLK1 as an attractive target for cancer therapy (Liu, 2015 ▸)." (PMID 41246821, 2025). "Given its frequent overexpression in various tumor types and its association with poor clinical outcomes, PLK1 has emerged as a highly attractive target for the development of anti-cancer therapies." (PMID 40612941, 2025). "In previous literature, the researchers identified potential nsSNPs of PLK1 from 24 missense SNPs that are associated with various cancer types." (PMID 41404416, 2025). "Following that, a wide range of computational tools like SIFT, PolyPhen-2, E-SNPs and GO, MutPred2, FATHMM-XF, I-Mutant 2.0, CUPSAT, DynaMut2, mCSM, and so on were utilized for prioritizing high-risk nsSNPs of PLK1 in all types of cancers." (PMID 41404416, 2025). "PLK1 has been shown to be overexpressed and associated with poor patient outcomes in several human cancers, including HGSOC." (PMID 39831777, 2025). "In this review, we discuss the structure and function of PLK1, its multifaceted role in cancer biology, and its significance and underlying mechanisms in the context of cancer immunotherapy." (PMID 40612941, 2025). "PLK1 is overexpressed in various malignant tumors, which is associated with poor prognosis of cancer patients." (PMID 40355412, 2025). "The polo-like kinase 1 (PLK1), a master key mitotic regulator, is frequently expressed in various types of cancers and associated with poor prognosis." (PMID 41404416, 2025). "A total of 207 nsSNP mutations of PLK1 were retrieved from cBioPortal by analyzing all types of cancers." (PMID 41404416, 2025). "Upregulation of PLK1 has been implicated in multiple cancers, making PLK1 a promising target for anticancer therapies." (PMID 41227386, 2025). "Subsequently, the overexpression of PLK1 is frequently linked to poor prognosis and its predominantly limited treatment choices, making it a potential target for cancer diagnostics and therapeutics." (PMID 41404416, 2025).
cancer (continued). "Extensive research has demonstrated that PLK1 is overexpressed in various human cancers, with elevated levels being associated with poor prognosis in tumors such as breast, lung, and colorectal cancers." (PMID 40190550, 2025). "Numerous studies, including The Cancer Genome Atlas (TCGA) cohort analysis, have shown that overexpression of Plk1 is present in multiple types of cancer and is closely associated with aggressive behavior and poor prognosis." (PMID 40166466, 2025). "The mitotic arrest caused by Plk1 inhibition is at least partially due to the presence of unrepaired double-strand breaks in mitosis in cancer cells." (PMID 40166466, 2025). "The study highlights the structural and functional implications of oncogenic PLK1 mutations, emphasizing their role in cancer progression." (PMID 41404416, 2025). "PLK1, a serine/threonine kinase involved in cell cycle regulation, is known to participate in various cancer-associated signaling pathways." (PMID 41284701, 2025). "Studies have found that PLK1 is overexpressed in several cancers including LUAD, and is associated with a poor prognosis." (PMID 40405133, 2025). "It demonstrated that PLK1 inhibition causes G2/M arrest and leads to apoptosis in various cancer cell lines." (PMID 39763588, 2024). "Lastly, PLK1, a key regulator of various stages of mitosis, is commonly overexpressed in many cancers and is associated with poor prognosis and increased tumor cell proliferation." (PMID 39201599, 2024). "Overexpression of PLK1 has been closely associated with poor prognosis and survival, as this has been seen in different types of cancer like breast, lung, ovarian carcinoma, and others." (PMID 38886738, 2024). "Polo-like kinase 1 (PLK1) is a serine/threonine protein kinase involved in cell cycle regulation, and aberrant PLK1 signaling has been implicated in various cancers, including HCC." (PMID 38255993, 2024). "Herein, we uncovered that the PLK1 inhibitors prefers to inhibit the growth of HCC cancer cells harbouring TERT promoter mutations." (PMID 38769666, 2024). "Aberrant regulation of PLK1 has been observed in numerous human cancers and is linked to poor prognoses." (PMID 39451218, 2024). "Both our lab and others have proven that PLK1 overexpression in LUAD leads to cancer progression and is associated with poor overall survival." (PMID 38885192, 2024). "In many types of cancer, the expression of PLK1 is upregulated, and its overexpression is usually associated with poor patient survival, including melanoma, breast cancer, and prostate cancer." (PMID 38057358, 2024). "The significant upregulation of PLK1 has been found in various human cancers and is significantly associated with poor prognosis in various cancers." (PMID 38783288, 2024). "PLK1, which is less expressed during the mitotic phase of normal cells but highly expressed in most human cancer tissues, has been associated with poor prognosis in various cancers, including HCC." (PMID 38255993, 2024). "The ANRS consists of five ANRGs: SPIB, CD24, NTRK3, EDA2R, and PLK1, all of which have been extensively linked to cancer." (PMID 39596658, 2024). "Elevated levels of PLK1 have been observed in numerous human cancers and are linked to poorer prognoses in these conditions." (PMID 39456780, 2024). "Analysis revealed that molecule 95 and 97 show potential as novel PLK1 inhibitors, opening up new possibilities for the targeted treatment of associated cancers." (PMID 38393054, 2024). "First, most patients enrolled in this study had missing information about cancer stage, treatment and prognosis data, which restricted the study of the association between PLK1 mutation subtypes and treatment efficacy." (PMID 38887977, 2024).
cancer (continued). "Four key genes CCL2, CCR7, LY96, and PTPRC, from ClusterK1 and five genes AURKA, CDK1, CCNA2, FEN1, and PLK1 from ClusterK2, were associated with at least one type of cancer." (PMID 38872418, 2024). "In this context, PLK1 overexpression in cancer cells is associated with poor prognosis and has been suggested as a potential target for cancer therapeutic interventions." (PMID 39273409, 2024). "This study connects the interaction between PLK1 and RhoGDI1 to the promotion of cancer cell behavior associated with malignant progression, thereby providing opportunities for cancer therapeutic interventions." (PMID 38355643, 2024). "APC-targeted proteins, such as CDC20, Securin, HURP, FOXM1, PLK1, and the Aurora kinases, accumulate in multiple unrelated cancer types and are generally associated with more aggressive disease and worse clinical outcomes." (PMID 38730707, 2024). "Studies of patient tumor samples have revealed a positive association between PLK1 expression and histopathologic grading in numerous human cancers, including ovarian, prostate, and gastric cancers." (PMID 37174744, 2023). "PLK-1 (Polo-like kinase-1) plays an essential role in cytokinesis, and its aberrant expression is considered to be keenly associated with a wide range of cancers." (PMID 36985522, 2023). "PLK1 overexpression occurs in a variety of human cancers; it is also associated with a poor prognosis." (PMID 36765811, 2023). "As important components of the cell cycle, high levels of UBE2C and PLK1 are commonly associated with aggressive cancers and poor patient prognoses for multiple cancer types." (PMID 37958642, 2023). "The aberrant expression of PLK-1 was found in many malignant tumors and was strongly associated with poor prognosis." (PMID 36985522, 2023). "High PLK1 expression has additionally been associated with poorer patient outcomes in several human cancers, including lung cancer, head and neck squamous cell carcinoma, and oropharyngeal cancer." (PMID 37174744, 2023). "The survival analyses revealed that the high expression of UBE2C was significantly associated with a poor prognosis in patients of 10 cancer types while PLK1 was also associated with 11 cancer types." (PMID 37958642, 2023). "The overexpression of PLK1 is a hallmark of many types of human cancers, including melanoma, ovarian carcinoma, breast, prostate, thyroid cancers, and glioma, and it is associated with chemoresistance and poor patient outcomes." (PMID 36902175, 2023). "Dysregulation of PLK1 has been linked to the emergence of many cancers, including breast, lung, pancreatic, prostate, and ovarian cancers, as well as non-Hodgkin’s lymphomas." (PMID 37765111, 2023). "High PLK1 expression is a common feature in numerous cancer types, and elevated PLK1 levels have been linked to aggressive tumor traits, including TNBC, vascular invasion, high proliferation rates, and poor prognostic implications in BC." (PMID 38234395, 2023). "Serine/threonine‐protein kinase PLK‐1, also known as polo‐like kinase 1 (PLK‐1), has been implicated in many different cancers, therefore targeting PLK‐1 represents one of the novel therapeutics for cancer treatment." (PMID 36925702, 2023). "Polo-like kinase 1 (PLK-1), a kinase that plays a crucial role in cell division, is overexpressed in many types of human cancers, which is associated with a poor prognosis." (PMID 37958980, 2023). "Herein, we will focus on PLK1, which has generated significant interest as a therapeutic target due to its overexpression in many human cancers and its association with higher tumor grade and poorer patient outcomes." (PMID 37174744, 2023). "Overexpression of PLK1 has been identified in multiple cancer types, and is associated with cell proliferation, EMT, apoptosis and chemotherapy resistance." (PMID 37872147, 2023). "Tumor cells will cause mitotic catastrophe and apoptosis in a variety of cancers when PLK1 activities are inhibited." (PMID 37305386, 2023).
cancer (continued). "The MYC-target gene PLK1 is a well-known cell cycle regulator and oncogene, implicated in the development of several cancer types." (PMID 37183219, 2023). "The tight regulation of PLK1 during the cell cycle is essential to mitotic progression and increased levels of PLK1 have been associated with cancer." (PMID 37684042, 2023). "Another protein that plays an important role in the cell cycle and its increased expression in many cancers and is considered the cause of invasion and metastasis is PLK1." (PMID 35928368, 2022). "This was critical, as PLK1 is implicated in enhanced cell motility and can drive cancer progression." (PMID 35454120, 2022). "While PLK1 mutations are extremely rare in human cancers, it is often found overexpressed, especially in advanced cancers." (PMID 35719948, 2022). "Because PLK1 is highly expressed in cancer cells and is associated with the poor prognosis of many cancers, it has emerged as a new target for developing many anticancer drugs." (PMID 36059955, 2022). "Various studies reported that the PLK1 overexpression is associated with cancer progression and drug resistance." (PMID 35008374, 2022). "Studies have demonstrated that PLK1 is usually overexpressed in a variety of cancers in human, including OSA (hOSA), and is broadly associated with a poor prognosis and disease progression." (PMID 36054794, 2022). "PLK1 gene alteration was the most frequent in UCEC patients among 32 cancer types, and was mainly represented as mutation." (PMID 36618405, 2022). "Increasing evidence demonstrated that PLK1 was overexpressed in various malignant tumors, and its upregulation was associated with the poor prognosis of cancer patients." (PMID 36267972, 2022). "Synthetic lethal drug screening reported that KRAS-mutated cancer cells seem vulnerable to PLK1 inhibition and depend more heavily on PLK1 activity for mitotic progression." (PMID 36142803, 2022). "PLK1 is predominantly related to regulation of the cell cycle, disruption of which is the primary cause of cancer." (PMID 36297281, 2022). "Overexpression of PLK1 has been found in many human cancers, which was associated with poor survival in cancer patients." (PMID 36476988, 2022). "In previous studies, PLK1 expression was associated with drug resistance in various cancer cells, and a high expression level of PLK1 was associated with a poor prognosis in NSCLC through the Kaplan-Meier plotter analysis." (PMID 35910374, 2022). "GO enrichment revealed major biological processes and pathways associated with CCND1/CDK4/PLK1/CD44 in different cancers." (PMID 34063946, 2021). "Considering that PLK1 is significantly associated with various cancers, the unique chemical scaffold described in this study will be valuable for developing new molecules as potential therapeutic agents for this disease." (PMID 33917995, 2021). "As a key regulator of cell division and DNA damage response, PLK1 was reported to be implicated in the development of various cancers, including HCC 3, 55-58." (PMID 33500714, 2021). "PLK1 has proved to have strong clinical relevance as it was found to be over-expressed in different cancer types and linked to poor patient prognosis." (PMID 34065956, 2021). "High levels of PLK1 are widely linked to oncogenic transformation, cancer progression, invasiveness, high metastatic potential and, importantly, poor overall patient survival." (PMID 34065956, 2021). "Studies have revealed the role of PLK1 in most human cancers, and established a causal association between PLK1 and hepatocarcinogenesis." (PMID 34899687, 2021). "On the one hand it is considered as an oncogene closely linked to human cancer development and on the other hand tumor suppressor functions are attributed to PLK1." (PMID 34065956, 2021). "WEE1 (as well as PLK1) is inhibited by adavosertib, and inhibition in cancer cells causes cell death in mitosis due to the induction of DNA damage and unsupervised entry of mitosis." (PMID 34071997, 2021).
cancer (continued). "In our study, PLK1 was found to impart aberrant post‐transcriptional regulation of cancer‐associated ARE‐coding genes that are associated with increased abundance and stability of ZFP36/TTP, likely due to increased phosphorylation." (PMID 33411958, 2021). "Collectively, these results suggest that a FBXW7-MYC-PLK1 signaling circuit underlies the tumorigenesis of MB and validate PLK1 inhibitors as potentially effective therapeutics for MYC-overexpressing cancers." (PMID 33494392, 2021). "PLK1 inhibition caused accelerated mRNA decay in cancer cells and was associated with reduced phosphorylation and stability of the mRNA decay‐promoting protein, tristetraprolin (ZFP36/TTP)." (PMID 33411958, 2021). "Previous studies have shown that plk1 is highly expressed in most human cancer, and its over-expression is associated with poor prognosis in patients." (PMID 33750965, 2021). "PLK1 overexpression induces and is linked to these epithelial-mesenchymal transition-associated key events via activation of defined and cancer-type specific signaling cascades." (PMID 34065956, 2021). "The overexpression of PLK1 was found in various types of cancers and was associated with poor prognosis of cancer patients." (PMID 33354424, 2020). "PLK1 is highly expressed in many human cancers and its overexpression is associated with a poor prognosis." (PMID 33304656, 2020). "PLK-1 has been recorded to be over-expressed in various human cancers and is associated with poor prediction; thus it is an attractive target for anticancer therapy." (PMID 35498298, 2020). "PLK1 was found to be up-regulated in many different types of cancer, in fact, it has been proposed as a novel diagnostic marker for several tumors." (PMID 33334055, 2020). "Studies have shown that PLK1 is highly expressed in most human carcinoma, and its overexpression is associated with an unfavorable prognosis 41-43." (PMID 33123291, 2020). "Studies have shown that PLK1 is highly expressed in most human carcinoma, and its overexpression is associated with unfavorable prognosis." (PMID 33178836, 2020). "PLK1 has been reported to be upregulated in various cancers and their expression level are associated with a poor prognosis and a lower overall-survival in many cancers including HNSCC." (PMID 31692905, 2019). "Accordingly, high expression of Plk1 is associated with higher aggressiveness in different types of cancers." (PMID 29541386, 2018). "PLK1 was reported to be overexpressed in various cancers and thought to confer tolerance of cells to cancer associated cellular stress." (PMID 30042885, 2018). "Plk1 inhibitors have been previously reported to induce loss of cell viability and apoptosis in different cancer cell lines." (PMID 29541386, 2018). "Altogether, these data suggest that the PLK1 expression is negatively associated with the Treg cell activity in a wide range of cancers." (PMID 30631355, 2018). "It is interesting to note that all six top-ranked genes proposed to be cancer-associated (PLK1, MCM2, MCM3, MCM7, MCM10 and SKP2) were downregulated by MP-HX in both cell lines." (PMID 30042885, 2018). "Strikingly, we found that higher PLK1 expression levels were significantly associated with higher CTA enrichment levels in 31 of the 33 cancer types (Spearman correlation, FDR<0.1)." (PMID 30631355, 2018).